OSBPL1A (oxysterol binding protein like 1A)
Description:
Binds phospholipids; exhibits strong binding to phosphatidic acid and weak binding to phosphatidylinositol 3-phosphate (By similarity). Stabilizes GTP-bound RAB7A on late endosomes/lysosomes and alters functional properties of late endocytic compartments via its interaction with RAB7A. Binds 25-hydroxycholesterol and cholesterol.
Synonyms: ORP-1; ORP1; OSBPL1B
Tractability: Small molecule: a structure with a bound ligand is known. Antibody: its Gene Ontology location is reachable by antibodies, with medium confidence. PROTAC: ubiquitination databases record sites on it; its protein half-life has been measured.
Gene: Protein-coding gene on chromosome 18 (24,162,045 to 24,397,880, reverse strand). Ensembl gene ENSG00000141447.
Subcellular location: Late endosome
Subcellular location (Human Protein Atlas): Cytosol; Nucleoplasm
Pathways (Reactome):
Immune System: MHC class II antigen presentation
Metabolism: Synthesis of bile acids and bile salts
Gene Ontology:
Molecular function: protein binding; sterol sensor activity; cholesterol binding; phospholipid binding; sterol transfer activity; lipid binding
Biological process: cholesterol homeostasis; lysosome to ER cholesterol transport; bile acid biosynthetic process; cholesterol metabolic process; vesicle-mediated transport; intracellular cholesterol transport
Cellular component: endoplasmic reticulum-endosome membrane contact site; endosome; extracellular exosome; late endosome; organelle membrane contact site; cytosol; perinuclear endoplasmic reticulum; plasma membrane; cytoplasm
Genetic constraint (gnomAD): Loss-of-function variants: 64 observed, 103.5 expected, observed/expected ratio (o/e) 0.62, 90% interval 0.5 to 0.76. The upper end of that interval is the gene's LOEUF score, 0.76, which puts it in group 3 of 6, group 1 being the genes least tolerant of losing a copy. Missense variants: 742 observed, 917.77 expected, observed/expected ratio (o/e) 0.81, 90% interval 0.76 to 0.86. Synonymous variants: 301 observed, 326.97 expected, observed/expected ratio (o/e) 0.92, 90% interval 0.84 to 1.01.
Homologues: Orthologues: chimpanzee OSBPL1A (99% identical), macaque OSBPL1A (98% identical), pig OSBPL1A (95% identical), dog OSBPL1A (95% identical), guinea pig OSBPL1A (94% identical), rabbit OSBPL1A (93% identical), mouse Osbpl1a (92% identical), rat Osbpl1a (89% identical), tropical clawed frog osbpl1a (75% identical), zebrafish osbpl1a (69% identical), Drosophila melanogaster CG3860 (25% identical), Caenorhabditis elegans obr-2 (17% identical). Paralogues in human: OSBPL2 (34% identical), OSBPL6 (25% identical), OSBPL3 (25% identical), OSBP2 (25% identical), OSBP (24% identical), OSBPL7 (23% identical), OSBPL5 (17% identical), OSBPL8 (17% identical), OSBPL10 (16% identical), OSBPL9 (14% identical), OSBPL11 (14% identical).
Diseases named in the same sentence as OSBPL1A in open-access papers:
OSBPL1A is named in the same sentence as 19 diseases in open-access papers, as found by Europe PMC text mining. Sharing a sentence is not in itself a finding about the gene and the disease. The quoted sentences say what the papers report.
colorectal cancer (2 papers, 2011 to 2024). A primary or metastatic malignant neoplasm that affects the colon or rectum. "Current research on OSBPL1A is limited, but existing studies suggest that it influences the production of HDL-C in the liver and intestines in conjunction with ABCA1 and also acts as a crucial prognostic factor in colorectal cancer." (PMID 38440405, 2024).
brain glioma (1 paper, 2011). A malignant glioma that involves the brain. "Significant expression changes of the OSBPL1A isoforms were observed in gastric and prostate cancer and metastases from prostate cancer patients along with brain gliomas." (PMID 21999571, 2011).
breast carcinoma (1 paper, 2022). "APOL3, APOL4, NR1H3, OSBPL1A, MAP2K6, and ZDHHC8 were protective genes for breast cancer prognosis." (PMID 35919504, 2022).
colorectal adenoma (1 paper, 2011). An adenoma that arises from the colon or rectum. "Alternative TSS usage in colorectal adenoma and cancer samples has been shown for nine genes, and OSBPL1A and TRAK1 were found to be regulated in vitro by Wnt signaling." (PMID 21999571, 2011).
dyslipidemia (1 paper, 2022). "The familial loss-of-function mutation in OSBPL1A affects the first step of the reverse cholesterol transport process and is associated with a low HDL-C phenotype, suggesting that rare mutations in the OSBPL gene may contribute to dyslipidemia." (PMID 35919504, 2022).
epilepsy (1 paper, 2026). A brain disorder characterized by episodes of abnormally increased neuronal discharge resulting in transient episodes of sensory or motor neurological dysfunction, or psychic dysfunction. "We demonstrated that HAGH, OSBPL1A, and PANK2 constitute core pathogenic mechanisms in epilepsy." (PMID 41810643, 2026).
lipid metabolism disorders (1 paper, 2025). "Mutations in OSBPL1A are associated with lipid metabolism disorders and may alter membrane structure, contributing to various metabolic diseases." (PMID 40290445, 2025).
Obesity (1 paper, 2012). Accumulation of substantial excess body fat. "Among 5 selected polymorphisms (rs9594738 of RANKL, rs17066364 of NUFIP1, rs7227401 of OSBPL1A, and rs1856057 and rs2982573 of ESR1) analyzed, 2 polymorphisms (rs9594738 and rs17066364) were associated with obesity-related traits." (PMID 23300848, 2012).
tumor (5 papers, 2011 to 2025). "This was in agreement with our mRNA expression levels as the short OSBPL1A variant is downregulated in cancer samples, whereas the long OSBPL1A variant was expressed at similar levels in the normal and tumor samples." (PMID 21999571, 2011). "This suggests that OSBPL1A and its associated signaling pathways may serve as potential therapeutic targets for anti-tumor strategies." (PMID 40290445, 2025). "In summary, the experiments confirmed that the tumor associated alternative TSS usages observed for TCF12, OSBPL1A and TRAK1 were indeed due to altered expression in the carcinoma cells, and not a consequence of altered tissue composition." (PMID 21999571, 2011). "Notably, significant functional differences are predicted between the long or short isoforms of TCF12, OSBPL1A, TRAK1, CHEK1, ANK3, LMO7 and SCIN indicating that the observed tumor associated changes in TSS usage probably have an impact on the growth properties of the neoplastic cells." (PMID 21999571, 2011). "Notably, AKR1B1, CD36, ABCA1, PRKD1, OSBPL1A, and FABP3 showed varied expressions in specific cells, suggesting their significant roles in STAD carcinogenesis, further confirmed by elevated mRNA levels in tumor tissues via qRT-PCR." (PMID 38440405, 2024).
cancer (3 papers, 2011 to 2025). A tumor composed of atypical neoplastic, often pleomorphic cells that invade other tissues. "For OSBPL1A, a primer set measuring the long variant showed expression in half of the cancer and the cancer derived stroma samples, whereas the expression in the normal epithelium was low in all but one sample." (PMID 21999571, 2011). "First, IHC analysis showed a significant difference in the total protein level of TCF12 and OSBPL1A between normal and cancer samples consistent with the mRNA expression pattern we observed." (PMID 21999571, 2011). "Research on OSBPL1A in cancer is limited, and its role in tumors remains unclear." (PMID 40290445, 2025). "Mitochondrial proteins OSBPL1A and ACACB can enhance radiosensitivity, reduce drug resistance, and offer new hope for treating recurrent cancer." (PMID 40290445, 2025). "The changes observed for CHEK1, OSBPL1A and TCF12 were confirmed in several other cancer types indicating that the change in TSS usage is a general mechanism in cancer biology." (PMID 21999571, 2011). "The shift in OSBPL1A isoform ratio was experimentally shown to be regulated by the Wnt pathway, which is deregulated not only in CRC, but also in many other cancer types." (PMID 21999571, 2011).
infection (3 papers, 2023 to 2024). The state of being infected such as from the introduction of a foreign agent such as serum, vaccine, antigenic substance or organism. "When comparing DEG in both SARS-CoV-2-infected groups at day 2 (i.e., 2 days after SARS-CoV-2-only infection and 4 days after H1N1 infection in the dual-infected group), only five known genes (Cd3d, Ctsw, Kirrel2, Osbpl1a and Aurkb) were differentially expressed at padj < 0.05." (PMID 38400021, 2024).
adenocarcinoma (1 paper, 2011). A common cancer characterized by the presence of malignant glandular cells. "To investigate the association between recurrence-free survival and TCF12 or OSBPL1A expression, we used a TMA containing biopsies from 268 stage II adenocarcinomas." (PMID 21999571, 2011).
OSBPL1A also shares sentences with these, for which no sentence is quoted: adenoma (1 paper); brain cancer (1); gastric cancer (1); metabolic disease (1); osteoporosis (1); prostate adenocarcinoma (1); prostate carcinoma (1).